S100A9 (S100 calcium binding protein A9)
Diseases named in the same sentence as S100A9 in open-access papers (continued):
Sharing a sentence is not in itself a finding about the gene and the disease.
colorectal cancer (50 papers, 2009 to 2025). A primary or metastatic malignant neoplasm that affects the colon or rectum. "Elevated plasma concentration of exosomal S100A9 was linked to the occurrence and recurrence of colorectal cancer." (PMID 36901813, 2023). "Granulocytic MDSCs express high concentrations of exosomal S100A9 that enhance colorectal cancer cell stemness and the susceptibility of mice to azoxymethane/dextran sulfate sodium-induced colitis-associated colon cancer." (PMID 36233088, 2022). "Interestingly, S100A8 and S100A9, whose products form the heterocomplex calprotectin, are strongly up-regulated in our study, in agreement with reports on inflammation-associated cancer and in human colorectal carcinomas." (PMID 20459814, 2010). "S100A9 is highly expressed in exosomes derived from PMN-MDSCs, and its blockade suppresses the stemness of colorectal cancer cells while reducing the susceptibility of mice to azoxymethane/dextran sulfate sodium-induced colitis-associated colon cancer." (PMID 41368628, 2025). "It facilitated the Polarization of M2 macrophage and increased the progression of colorectal carcinoma via inducing TLR4/NF-κB/S100A9 Cascade." (PMID 41326479, 2025). "Using diverse techniques like ELISA, immunohistochemistry, and biodatabase analysis, we found that S100A8 and S100A9 expression levels were significantly elevated in colorectal cancer patient tumor tissues compared to normal tissues." (PMID 38817853, 2024). "For S100A9, the baseline concentration was 10.05 (7.68–15.34) ng/mL in healthy controls and increased up to 22.32 (14.88–29.55) ng/mL in colorectal cancer patients." (PMID 39768997, 2024). "To better understand the localization of S100A8 and S100A9 in cancer tissues, we conducted immunohistochemical analyses on human colorectal cancer samples." (PMID 38817853, 2024). "Our previous findings indicated a significant increase in both RNA and protein levels of S100A8 and S100A9 in colorectal cancer tissues, suggesting a correlation with the malignancy and prognosis of the lesions." (PMID 38817853, 2024). "Our immunohistochemical analyses further confirmed the significant increase in the cytoplasmic presence of S100A8 and S100A9 in the glandular epithelial cells of colorectal cancer tumors compared to normal tissues." (PMID 38817853, 2024). "Functional models of high S100A8/S100A9 expression in colorectal cancer cells were established through transfection with overexpression plasmids." (PMID 38817853, 2024). "These considerations underscore the necessity for future studies to broaden the scope of our findings and facilitate a deeper understanding of the intricate interactions between S100A8, S100A9, and the tumor microenvironment in colorectal cancer." (PMID 38817853, 2024). "Blocking S100A9 expression in MDSCs-Exos can inhibit the stemness of colorectal cancer cells and prevent the occurrence of colon cancer in mice with colitis." (PMID 35154134, 2022). "The S100A9 protein (calgranulin B) has a strong proinflammatory impact, stimulates chemotaxis, exerts a tumor-promoting effect in colorectal carcinoma and stimulates its neoplastic progression." (PMID 33466593, 2021). "In general, as early diagnosis biomarkers of colorectal cancer, S100A9 and TNC levels are comprehensive." (PMID 31632476, 2019). "S100A9 is a potential therapeutic target for various disease including prostate cancer, colorectal cancer, and Alzheimer's disease." (PMID 31824919, 2019). "In colorectal cancer patients who were diagnosed in advanced stages or with distant metastases, serum S100A9 concentrations were higher on average." (PMID 31632476, 2019). "In prostate cancer, benign prostate hyperplasia, and colorectal cancer, serum S100A8 and S100A9 are shown to have diagnostic potential." (PMID 30808902, 2019). "We previously showed that the proinflammatory molecule S100A9 in TME exerts a tumor-promoting effect in colorectal carcinoma (CRC)." (PMID 31620141, 2019).
colorectal cancer (continued). "The striking expression patterns observed from anti-S100a9 Ab treatment of AOM/DSS-induced CRC mice prompted us to perform additional analysis across human colorectal carcinoma." (PMID 29326691, 2017). "In contrast, there are a couple of previous publications, which suggest that S100A9 directly regulates the tumor developments as well as metastasis in human colorectal cancer patients." (PMID 26431492, 2015). "Expression of S100A8 and S100A9 in paired of colorectal carcinoma and matched distal normal tissues." (PMID 23637971, 2013). "Then the influence of S100A8 and S100A9 in the viability and migration of human colorectal carcinoma cell lines (HCT116 and SW480) and in Wnt/β-catenin pathway was analyzed." (PMID 23637971, 2013). "Expression of S100A8 and S100A9 in colorectal carcinoma and matching distal normal tissues were measured by reverse transcriptase polymerase chain reaction (RT-PCR), immunohistochemistry and western blot." (PMID 23637971, 2013). "Our results agree with previous studies demonstrating high expression of S100A9 in infiltrating immune cells in various cancer types including colorectal cancer and pancreatic cancer." (PMID 22838504, 2012). "The proteins that showed the greatest degree of overexpression in primary colorectal cancer compared with normal colonic mucosa were heat shock protein 60 (p<0.001), S100A9 (p<0.001) and translationally controlled tumour protein (p<0.001)." (PMID 22125622, 2011). "Furthermore, our Western blot analysis revealed heightened expression levels of S100A8 and S100A9 in colorectal cancer cells SW480, SW620, and CT26 when compared to normal colonic epithelial cells NCM460." (PMID 38817853, 2024). "Granulocytic myeloid-derived suppressor cells were shown to enhance the capability of colorectal cancer cells for self-renewal and differentiation as a result of exosomes and exosomal S100A9 influence in the tumor microenvironment, mainly under hypoxic conditions." (PMID 36901813, 2023). "The level of plasma S100A9 expressed in exosomes in patients with colorectal cancer is significantly increased compared with that in normal controls, and the serum level in patients with recurrent tumors is increased compared with that in patients with successful resection of colorectal cancer." (PMID 35154134, 2022). "MDSCs-Exos aggravate the stemness of colorectal cancer cells through exosomal S100A9." (PMID 35154134, 2022). "Consequently, MDSC-Exo S100A9 can be used as a marker to predict the occurrence and development of colorectal cancer." (PMID 35154134, 2022). "S100A9 regulates immune suppression via RAGE in colorectal cancer." (PMID 32903598, 2020). "The combination of S100A9, TNC and CEA levels was more specific and sensitive than the combination of CEA and CA19-9 levels as a diagnostic biomarker of colorectal cancer, and we created a more efficient method to diagnose colorectal cancer." (PMID 31632476, 2019). "For instance, studies have shown that the S100A8/S100A9 complex, which has a broad range of intracellular and extracellular functions, suppresses keratinocyte proliferation, but promote the growth and metastasis of colorectal cancer cells." (PMID 29872130, 2018). "S100 calcium-binding protein A9, annexin A3, nicotinamide phosphoribosyltransferase, carboxylesterase 2 and calcium activated chloride channel A1 were probably potential biomarkers of colorectal cancer." (PMID 27661117, 2016). "In addition, S100A9 was significantly higher in stool samples of colorectal cancer patients than in controls." (PMID 22838504, 2012). "Furthermore, differential analysis and pathway enrichment studies revealed a strong correlation between the levels of S100A8/S100A9 and inflammatory signaling pathways in these patients, underscoring their essential roles in the advancement and progression of colorectal cancer." (PMID 38817853, 2024). "However, the precise function of high S100A8/S100A9 expression in colorectal cancer cells remains unclear." (PMID 38817853, 2024).
colorectal cancer (continued). "Furthermore, our data also show that extracellular S100A8 and S100A9 could promote viability and migration of colorectal cancer cell lines HCT116 and SW480 through upregulation of Wnt/β-catenin pathway." (PMID 23637971, 2013). "This study also demonstrates that hypoxia induced exosomal S100A9 increases the phosphorylation of STAT3 and NF-κB p65 in colon cancer cells and enhances colorectal cancer occurrence and recurrence." (PMID 39928285, 2025). "We obtained the expression matrix for colorectal cancer patients from the TCGA database and conducted a differential analysis based on the expression levels of S100A8 and S100A9." (PMID 38817853, 2024). "More importantly, through the activation of S100A9, NGFR enhances the chemosensitivity of colorectal cancer cells by promoting the apoptotic and autophagic effects of 5-fluorouracil." (PMID 36518255, 2022). "Further analysis indicates that hypoxia induces granulocytic MDSCs to produce more S100A9-enriched exosomes in an HIF-1α-dependent manner, leading to promoted colorectal cancer cell stemness and growth." (PMID 36233088, 2022). "Our work demonstrated that S100A8 and S100A9 are linked to the CRC progression, and one of the underlying molecular mechanisms is that extracellular S100A8 and S100A9 proteins contribute to colorectal carcinoma cell survival and migration via Wnt/β-catenin pathway." (PMID 23637971, 2013). "It was reported previously that S100A9 is up-regulated in conjunction with S100A8 in many cancers, including gastric cancer, prostate cancer, and colorectal cancer." (PMID 20096140, 2010). "Both S100A9 and TNC levels have the potential identify colorectal cancer." (PMID 31632476, 2019). "Culture of human colorectal cancer cells HT29, HCT116 and LOVO in monocytes/macrophage-conditioned media similarly upregulated S100a8 and S100a9 mRNA expression in the cancer cells, indicating that induction of these genes by the conditioned media was not restricted to murine cell lines." (PMID 27086923, 2016).
melanoma (45 papers, 2008 to 2025). A malignant, usually aggressive tumor composed of atypical, neoplastic melanocytes. "This pattern is associated with a loss of basement membrane, suggesting an S100A9/EMMPRIN role in melanoma dissemination through the basement membrane and extracellular matrix degradation." (PMID 39201498, 2024). "Within the metal sequestration by the antimicrobial peptides pathway, the S100 family genes S100A7, S100A8, and S100A9 have been linked to tumor growth and metastasis in multiple cancers, including melanoma." (PMID 35008167, 2021). "Thus, the association of PRAME, CXCL9, CXCL10, S100A7, S100A8, and S100A9 with melanoma progression is supported by prior studies and commercially available clinical tests." (PMID 35008167, 2021). "S100A9 promotes metastasis in melanoma, and knockdown of S100A9 suppresses proliferation in glioma stem cells and inhibits the growth of xenograft tumors in vivo, suggesting an association between the tumorigenic potential of cancer stem cells and S100A9 upregulation." (PMID 31055998, 2019). "S100P and S10012 have a diagnostic and prognostic value in many human cancers, while the contribution of S100A8 and S100A9 to melanoma biology is not fully understood." (PMID 40075679, 2025). "EMMPRIN was first described in the context of S100 proteins when S100A9 was discovered to be a promoter of melanoma cell migration." (PMID 37056775, 2023). "The co-expression pattern of LYPD3 and S100A9 was confirmed by multiple immunofluorescence (mIF) staining of the same melanoma resection specimen." (PMID 37924160, 2023). "There is evidence that S100A9 induces cytokines and matrix metalloproteases (MMPs) in melanoma cells via binding to EMMPRIN." (PMID 37056775, 2023). "Our results show that S100A9 is expressed only in one tested melanoma cell line, A375 (BRAFV600E mut)." (PMID 36139698, 2022). "The S100A9‐targeted CPMV also was effective in treating lung metastasis from melanoma or TNBC after establishment of the disease." (PMID 34519180, 2021). "Recombinant S100A9, a calcium-binding protein A9, which is known as migration inhibitory factor has been shown to reduce the A-375 melanoma cell line proliferation and down-regulate OCLN gene expression in a time- and dose-dependent manner." (PMID 31754355, 2019). "cDNA analysis revealed an upregulation of S100A8 and S100A9 gene expression in melanoma metastases compared to primary melanomas." (PMID 31806053, 2019). "Profiling of melanoma EV cargo identified shared proteomic and RNA signatures including S100A8 and S100A9 protein cargo, which in vitro compromised DC maturation similar to melanoma EVs." (PMID 28424693, 2017). "S100A4 levels are lower in metastatic melanoma compared with primary tumors, while S100A7, S100A8, and S100A9 levels appear to be higher in malignant melanoma compared with normal melanocytes." (PMID 19859558, 2010). "Notably, our findings in a mouse model demonstrate that EMMPRIN interacts preferentially with S100A9, and this interaction promotes melanoma cell entry into the bloodstream and accumulation in skin tissue artificially enriched with S100A9." (PMID 40924339, 2025). "Moreover, for S100A8 and S100A9, overexpressed in mestastatic melanoma, in addition to their prognostic role, a predictive role in immunotherapy response has been evidenced." (PMID 38775220, 2024). "Interestingly, in primary melanoma, S100A9 and its receptor EMPRINN co-localize at the tumor-invasive edge and in the adjacent epidermis." (PMID 39201498, 2024). "Thus far, 8 out of 21 GLI targets we chose to validate—KRT16, S100A9, SOX9, BIRC7, EBI3, FLG, SAMMSON and SPRY2—were already implicated in melanoma pathogenesis." (PMID 36139698, 2022). "Our results generated by scRNA-seq analysis of PBMC in an initial discovery cohort of patients with melanoma indicated that S100A9 expression by monocytes in cluster 1 was one of the most differentially expressed genes between responders and non-responders to anti-PD1 therapy." (PMID 33963011, 2021).
melanoma (continued). "In vitro, Ab45 could inhibit S100A8/S100A9-stimulated chemotaxis, and in vitro significantly reduced lung metastasis within a melanoma model." (PMID 32722137, 2020). "MiR-92a-1-5p is also downregulated in BRAF inhibitor-resistant melanoma cell lines and one of its targets, S100A9 could play a role in resistance to BRAF inhibitors." (PMID 32183388, 2020). "However, melanoma cells express surface receptors like RAGE or CD147 that bind S100A8/S100A9, thereby migrate into tissues with high expression of S100A8 and S100A9 and initiate metastases." (PMID 31806053, 2019). "In addition, we identified PMEL exclusively in melanoma cells and S100A9 exclusively in PDAC cells." (PMID 38199984, 2024). "Importantly, we could confirm these findings in an independent patient cohort, which indicated a strong association between the presence of high frequencies of S100A9+ monocytes and reduced PFS in patients with melanoma undergoing PD-1 checkpoint blockade." (PMID 33963011, 2021). "High-plex spatial RNA profiling has been instrumental in revealing cell type-specific biomarker expression in the TME during early melanoma evolution, including prominent expression of S100A8 and S100A9 in melanoma-adjacent keratinocytes." (PMID 38217840, 2024). "S100A9 is suggested to have a role in acquired resistance to BRAF inhibitors and in melanoma metastasis." (PMID 36139698, 2022). "The myPath Melanoma Test utilizes the expression of 14 signature genes, including PRAME, CXCL9, CXCL10, S100A7, S100A8, and S100A9, and nine reference genes to distinguish BN from CMM." (PMID 35008167, 2021). "Profiling of melanoma EV cargo revealed shared proteomic and RNA signatures including S100A8 and S100A9 protein cargo." (PMID 34078376, 2021). "Further experiments showed that similar to melanoma EVs-treated DCs, the incubation of DCs with S100A8 and S100A9 proteins compromised their maturation in vitro." (PMID 34078376, 2021). "S100A9 binds to EMMPRIN, an inducer of MMP synthesis, to regulate MMP1 expression in a melanoma cell model." (PMID 33005006, 2020). "S100A8/S100A9 binds to the melanoma cell adhesion molecule (MCAM), a highly expressed cell adhesion molecule in melanoma." (PMID 32722137, 2020). "When monitoring stage IV melanoma patients during immunotherapy with ipilimumab, the heterodimer S100A8/S100A9 attracted attention, as high serum levels of it in early stages of treatment predicted worse response." (PMID 32722137, 2020). "Paclitaxel in ultra-low non-cytotoxic dose reduces both the number and immunosuppressive activity of MDSC, leading to increased survival of melanoma-bearing mice through p38 MAPK and S100A9 signaling." (PMID 32508809, 2020). "Taken together, these data suggest melanoma EV cargo, including established chronic inflammatory mediators S100A8 and S100A9 have the capacity to drive EV inhibitory effects on DC maturation." (PMID 28424693, 2017). "Consistent with this, we found that the pro-inflammatory cytokines S100A8 and S100A9, as well as the chemokine receptor CXCR4, were highly and significantly upregulated in primary melanomas compared to benign nevi." (PMID 26918341, 2016). "Genes such as KRT14, GJA1, S100A7, S100A9, and EHF were higher in most melanomas while genes such as CITED-1, GDF15, QPRT, OCA2, c-MET and MME were more highly expressed in NHEM." (PMID 18442402, 2008). "Moreover, S100A9 was found in two GBM cohorts and two melanoma cohorts as a robust tool for predicting cancer patients’ response to ICIs." (PMID 39137310, 2024). "Further evaluation results indicated that S100A9 could effectively predict the response of GBM patients to ICIs, which was also verified in two independent melanoma immunotherapy cohorts." (PMID 39137310, 2024). "Interestingly, melanoma-secreted exosomes were shown to induce a strong expression of S100A8 and S100A9 in human primary keratinocytes, but the exosomal components triggering this effect were not identified." (PMID 39201498, 2024).